PSEN1 (presenilin 1)
Description:
Catalytic subunit of the gamma-secretase complex, an endoprotease complex that catalyzes the intramembrane cleavage of integral membrane proteins such as Notch receptors and APP (amyloid-beta precursor protein). Requires the presence of the other members of the gamma-secretase complex for protease activity. Plays a role in Notch and Wnt signaling cascades and regulation of downstream processes via its role in processing key regulatory proteins, and by regulating cytosolic CTNNB1 levels. Stimulates cell-cell adhesion via its interaction with CDH1; this stabilizes the complexes between CDH1 (E-cadherin) and its interaction partners CTNNB1 (beta-catenin), CTNND1 and JUP (gamma-catenin). Under conditions of apoptosis or calcium influx, cleaves CDH1. This promotes the disassembly of the complexes between CDH1 and CTNND1, JUP and CTNNB1, increases the pool of cytoplasmic CTNNB1, and thereby negatively regulates Wnt signaling. Required for normal embryonic brain and skeleton development, and for normal angiogenesis (By similarity). Mediates the proteolytic cleavage of EphB2/CTF1 into EphB2/CTF2. The holoprotein functions as a calcium-leak channel that allows the passive movement of calcium from endoplasmic reticulum to cytosol and is therefore involved in calcium homeostasis. Involved in the regulation of neurite outgrowth. Is a regulator of presynaptic facilitation, spike transmission and synaptic vesicles replenishment in a process that depends on gamma-secretase activity. It acts through the control of SYT7 presynaptic expression (By similarity).
Synonyms: PS-1; AD3; PS1; PSNL1; FAD; S182; ACNINV3; CMD1U
Tractability: Small molecule: a drug acting on it is in phase 2 or 3 trials; a structure with a bound ligand is known; a high-quality ligand is known; it has a binding pocket of medium quality; it belongs to a druggable protein family. Antibody: UniProt places it where antibodies can reach, with high confidence; its Gene Ontology location is reachable by antibodies, with high confidence; UniProt predicts a signal peptide or a membrane-spanning region. PROTAC: ubiquitination databases record sites on it; its protein half-life has been measured; a small molecule that binds it is known.
Target class: Presenilin ER Ca2+ leak channel family; Ion channel; Other ion channel; Miscellaneous ion channel
Chemical probes: GSM1, MRK-560 (high quality), PF-06648671 (high quality)
Gene: Protein-coding gene on chromosome 14 (73,136,418 to 73,223,691, forward strand). Ensembl gene ENSG00000080815.
Subcellular location: Endoplasmic reticulum; Endoplasmic reticulum membrane; Golgi apparatus membrane; Cytoplasmic granule; Cell membrane; Cell projection, growth cone; Early endosome; Early endosome membrane; Cell projection, neuron projection; Cell projection, axon; Synapse
Subcellular location (Human Protein Atlas): Golgi apparatus; Cell Junctions; Nucleoplasm
Pathways (Reactome):
Signal Transduction: Activated NOTCH1 Transmits Signal to the Nucleus; NOTCH2 Activation and Transmission of Signal to the Nucleus; NOTCH3 Activation and Transmission of Signal to the Nucleus; NOTCH4 Activation and Transmission of Signal to the Nucleus; NRIF signals cell death from the nucleus; Noncanonical activation of NOTCH3; Nuclear signaling by ERBB4; Regulated proteolysis of p75NTR; TGFBR3 PTM regulation
Disease: Constitutive Signaling by NOTCH1 HD+PEST Domain Mutants; Constitutive Signaling by NOTCH1 PEST Domain Mutants
Developmental Biology: EPH-ephrin mediated repulsion of cells
Extracellular matrix organization: Degradation of the extracellular matrix
Immune System: Neutrophil degranulation
Gene Ontology:
Molecular function: aspartic endopeptidase activity, intramembrane cleaving; ATPase binding; beta-catenin binding; calcium channel activity; endopeptidase activity; growth factor receptor binding; molecular adaptor activity; PDZ domain binding; protein binding; aspartic-type endopeptidase activity; cadherin binding; peptidase activity
Biological process: amyloid precursor protein catabolic process; amyloid precursor protein metabolic process; amyloid-beta formation; astrocyte activation; astrocyte activation involved in immune response; cell-cell adhesion; cellular response to amyloid-beta; DNA damage response; endoplasmic reticulum calcium ion homeostasis; intracellular signal transduction; learning or memory; membrane protein ectodomain proteolysis; memory; negative regulation of apoptotic process; negative regulation of gene expression; neuron projection maintenance; Notch receptor processing; positive regulation of amyloid fibril formation; positive regulation of dendritic spine development; positive regulation of DNA-templated transcription; positive regulation of gene expression; positive regulation of glycolytic process; positive regulation of tumor necrosis factor production; protein processing; regulation of gene expression; and 17 more
Cellular component: aggresome; centrosome; dendrite; early endosome; endoplasmic reticulum; endoplasmic reticulum membrane; gamma-secretase complex; Golgi apparatus; Golgi membrane; growth cone; kinetochore; membrane; membrane raft; mitochondrion; neuron projection; nuclear membrane; nuclear outer membrane; nucleus; plasma membrane; protein-containing complex; rough endoplasmic reticulum; smooth endoplasmic reticulum; azurophil granule membrane; synapse; axon; and 18 more
Genetic constraint (gnomAD): Loss-of-function variants: 13 observed, 48.63 expected, observed/expected ratio (o/e) 0.27, 90% interval 0.17 to 0.43. The upper end of that interval is the gene's LOEUF score, 0.43, which puts it in group 1 of 6, group 1 being the genes least tolerant of losing a copy. Missense variants: 351 observed, 550.59 expected, observed/expected ratio (o/e) 0.64, 90% interval 0.58 to 0.7. Synonymous variants: 190 observed, 204.64 expected, observed/expected ratio (o/e) 0.93, 90% interval 0.82 to 1.05.
Gene-disease validity (ClinGen):
ClinGen rates the evidence that PSEN1 causes each of these diseases.
dilated cardiomyopathy 1U (autosomal dominant): Disputed.
Homologues: Orthologues: chimpanzee PSEN1 (100% identical), macaque PSEN1 (99% identical), rabbit PSEN1 (96% identical), guinea pig PSEN1 (96% identical), dog PSEN1 (94% identical), mouse Psen1 (93% identical), rat Psen1 (93% identical), pig PSEN1 (92% identical), tropical clawed frog psen1 (78% identical), zebrafish psen1 (70% identical), Drosophila melanogaster Psn (53% identical), Caenorhabditis elegans sel-12 (46% identical). Paralogues in human: PSEN2 (62% identical).
Diseases named in the same sentence as PSEN1 in open-access papers:
PSEN1 is named in the same sentence as 201 diseases in open-access papers, as found by Europe PMC text mining. Sharing a sentence is not in itself a finding about the gene and the disease. The quoted sentences say what the papers report.
Alzheimer disease (536 papers, 2005 to 2026). A progressive, neurodegenerative disease characterized by loss of function and death of nerve cells in several areas of the brain leading to loss of cognitive function such as memory and language. "Mutations of the PSEN1 gene are inherited as fully penetrant, autosomal-dominant traits, which almost always result in the clinical onset of Alzheimer's disease before the age of 65 years." (PMID 41579901, 2026). "The 3xTg‐AD mouse model is essential in AD pathology research due to the presence of APP, tau, and Psen1 genes associated with familial ad." (PMID 40589337, 2025). "PSEN1 E280A, also known as the “Paisa mutation,” has been identified as the primary cause of familial early-onset Alzheimer’s disease (FAD) in the state of Antioquia, Colombia." (PMID 40332390, 2025). "These mice express a chimeric amyloid precursor protein and human presenilin-1, previously found to have mutations associated with the development of Alzheimer’s disease." (PMID 40427569, 2025). "These are two brain-specific uncoupling proteins (SCL25A27 and SLC25A14) and three genes linked to Alzheimer Disease (PSEN1, PSEN2, and BACE1)." (PMID 40901366, 2025). "Common transgenic rat models, similar to mouse models, utilize APP and PSEN1 transgenes containing mutations representative of inherited Alzheimer’s disease." (PMID 40426657, 2025). "Familial Alzheimer’s disease (FAD) caused by presenilin 1 (PSEN1) E280A induces the aberrant accumulation of intracellular Aβ (iAβ) in cholinergic-like neurons (ChLNs)." (PMID 40332390, 2025). "Mutations in PSEN1 show complete penetrance and are causative for the most severe forms of Alzheimer’s disease with an onset as early as the third decade." (PMID 40869138, 2025). "Over 300 mutations in PSEN1 have been identified as causes of early-onset Alzheimer’s disease (EOAD)." (PMID 40909785, 2025). "Meanwhile, Psen1 functions as a causative factor for early onset Alzheimer’s disease, and as a part of γ-secretase, impacts Notch signaling and β-cadherin processing." (PMID 39703504, 2024). "In a model of Alzheimer’s disease (AD), 3xTg-AD mice which express AD-related mutations of the amyloid precursor protein, presenilin 1 and tau, hippocampal GluA2 surface expression was decreased." (PMID 39056071, 2024). "Research has demonstrated that mutations in the amyloid protein precursor (APP) and presenilin-1/2 (PS 1/2) genes lead to abnormal production of Aβ, which is strongly linked to the development of early onset Alzheimer’s disease (AD)." (PMID 39378198, 2024). "Amyloidosis, including cerebral amyloid angiopathy, and markers of small vessel disease (SVD) vary across dominantly inherited Alzheimer's disease (DIAD) presenilin‐1 (PSEN1) mutation carriers." (PMID 38380882, 2024). "Genetic studies offered insights into diverse mutations and risk associations, with the PSEN1 mutation being crucial in Alzheimer’s disease research." (PMID 39369726, 2024). "Research in Colombia is focused mostly on carriers of the PSEN1 E280A mutation, related to familial Alzheimer’s disease." (PMID 39369726, 2024). "Familial Alzheimer’s disease (FAD) can be caused by mutations in PSEN1 that encode presenilin-1, a component of the gamma-secretase complex that cleaves amyloid precursor protein." (PMID 38792645, 2024). "It is of interest to note that subjects carrying mutations in the presenilin-1 gene, a gene responsible of early-onset Alzheimer’s disease, frequently complained of headache even in the pre-symptomatic phase of the disease." (PMID 37721571, 2024). "PSEN1 is best known as a causative factor for early‐onset Alzheimer's disease (EOAD) and over 300 mutations in PSEN1 have been identified in relation to EOAD." (PMID 38031879, 2024). "The GSE3942 dataset contains 3 specimens (7 controls, 7 early-onset Alzheimer’s disease, 7 early-onset AD genetically determined by a mutation in PSEN1 gene)." (PMID 38528586, 2024).
Alzheimer disease (continued). "An important contributing factor to autosomal dominant early-onset Alzheimer’s disease (EOAD) is a mutation in the presenilin-1 (PS-1) gene (Hanisch and Kölmel, 2004)." (PMID 39640295, 2024). "Autosomal dominant Alzheimer's disease (ADAD) is a rare form of Alzheimer's disease (AD) that arises from mutations in the genes encoding presenilin 1 (PSEN1), presenilin 2 (PSEN2), or amyloid precursor protein (APP), all affecting APP processing." (PMID 38666355, 2024). "Psen1 is a Presenilin gene, and its mutation is associated with both early and late onset of Alzheimer’s disease (AD), which has been found to be highly correlated with depression." (PMID 39135796, 2024). "We saw mimics of autoimmune encephalitis including neurodegenerative diseases such as prion disease, PSEN1-associated young onset Alzheimer's disease." (PMID 37793287, 2023). "In Alzheimer’s disease, somatic mutations in the presenilin-1 (PSEN1) gene have been reported in peripheral lymphocytes (8%) and in the cerebral cortex (14%) derived from a patient with Alzheimer’s disease." (PMID 37834279, 2023). "The emerging world faces a genetic risk of Alzheimer’s disease (AD) due to mutations in PSEN1 (located on chromosome 14), PSEN2 (located on chromosome 1), and APP (located on chromosome 21), which are known to cause familial Alzheimer’s disease (FAD)." (PMID 38173557, 2023). "Current studies have shown that PSEN1 is mainly associated with Alzheimer’s disease, amyloidosis, cancer-related genes, cardiomyopathy, disease variation, and cognitive disorders." (PMID 37189611, 2023). "In this study, a selection of proteins related to the pathology of Alzheimer’s disease was modeled, with Presenilin-1 (PSN1) and its mutated variants in the foreground." (PMID 37686347, 2023). "Mutations in the amyloid-β precursor protein (APP) and Presenilin 1/2 (PSEN1/2) genes cause Familial forms of Alzheimer’s disease (FAD)." (PMID 37257821, 2023). "The presenilin-1 (PSEN1) gene was verified as one of the main causative factors for early onset Alzheimer’s disease (EOAD)." (PMID 37176125, 2023). "PSEN1, belonging to the aspartyl proteases family, is generally recognized as being associated with Alzheimer’s disease." (PMID 36219476, 2022). "The A413E (rs63750083) PSEN1 variant, identified in 2001, is associated with early-onset Alzheimer’s disease (EOAD)." (PMID 35959289, 2022). "PSEN1 c.839A>C (p.Glu280Ala), of European origin, is the largest family in the world with familial Alzheimer’s disease and living nearby is a family with the PSEN1 variant c.1247 T>C (p.Ile416Thr) that originated in Africa." (PMID 35260199, 2022). "PSEN1 is a recognized gene associated with Alzheimer's disease, which can induce the intramembrane division of Notch receptors and then activate Notch signaling pathways." (PMID 36042374, 2022). "We applied the proposed methods to mutated amyloid precursor protein and presenilin-1 mouse model of Alzheimer’s disease." (PMID 35309883, 2022). "Autosomal dominant Alzheimer’s disease (ADAD) accounts for approximately 1% of all Alzheimer’s disease (AD) cases and is usually caused by mutations in one of three known genes, namely PSEN1 (OMIM 104311), APP (OMIM 104760), and PSEN2 (OMIM 1600759)." (PMID 36380395, 2022). "Presenilin-1 (PSEN1) has been verified as an important causative factor for early onset Alzheimer’s disease (EOAD)." (PMID 36142879, 2022). "These mice express humanfamilial Alzheimer’s disease-associated mutations in amyloid precursorprotein and presenilin-1 and develop amyloid plaques andplaque-associated synapse loss similar to that observed in Alzheimer’sdisease brain." (PMID 35359460, 2022). "Familial Alzheimer's disease (FAD) is caused by autosomal dominant mutations in the PSEN1, PSEN2 or APP genes, giving rise to considerable clinical and pathological heterogeneity in FAD." (PMID 34319632, 2022).
Alzheimer disease (continued). "Presenilin-1 (PS-1), a component of the gamma (γ)-secretase catalytic complex, has been implicated in Alzheimer’s disease (AD) and in tumorigenesis." (PMID 35563300, 2022). "By means of this pipeline, a list of 32 prioritized Alzheimer’s disease (AD) genes were produced and two AD susceptibility genes including PSEN1 and TRAF1 were correctly identified." (PMID 36081461, 2022). "Variants in BACE1 and/or γ-secretase substrates, as well as variants in PSEN1, encoding the catalytic domain of γ-secretase, are linked to many pathophysiological conditions, including Alzheimer’s disease, epileptic encephalopathy, cardiac disease, and cancer." (PMID 33411695, 2021). "This appears to be the first worldwide data on the role of the presenilin 1 and 2 genes associated with Alzheimer’s disease in the dysregulation of neonatal lymphocytes after perinatal asphyxia." (PMID 34067945, 2021). "This cohort study investigates differences in cognitive functioning by sex and genetic variant status among Colombian children the autosomal dominant Alzheimer disease presenilin 1 E280A variant." (PMID 34463747, 2021). "Recent studies on post-ischemic brain neurodegeneration have revealed the dysregulation of Alzheimer's disease-associated genes such as amyloid protein precursor, α-secretase, β-secretase, presenilin 1, presenilin 2, and tau protein." (PMID 33679381, 2021). "In a small percentage of patients, Alzheimer’s disease (AD) is characterized by an early onset due to a mutation in one of three identified genes: amyloid-beta precursor protein (AβPP), Presenilin 1 (PSEN1), and Presenilin 2 (PSEN2)." (PMID 32581318, 2021). "It has been well established that mutations in the gene coding for presenilin-1 (PS-1) are a risk factor that predispose for development of Alzheimer’s disease." (PMID 34064983, 2021). "It has been well recognized that mutant PSEN1 (gain of function) is associated with the accumulation of amyloid beta (Aβ) and the onset of Alzheimer’s disease." (PMID 35054411, 2021). "Emerging evidence suggests that Alzheimer's disease has a pre-symptomatic period that can be 40–50 years long since PSEN1 E280A mutation carriers are showing cerebral spinal fluid abnormality as early as in their 20s28,29." (PMID 33420208, 2021). "Some of the cerebral cortex regulators included Psen1, and Mapt (Tau) which are associated with Alzheimer disease (AD)." (PMID 34429070, 2021). "The Presenilin1 (PS1) protein is encoded by the PSEN1 gene, which is located on chromosome 14 in humans, and has been well investigated in Alzheimer’s disease (AD)." (PMID 34781973, 2021). "The longer survival of these KI rats affords the opportunity to examine the effect of homozygous Psen1 Alzheimer's disease–associated mutations on neurodegeneration in older animals." (PMID 32265300, 2020). "Forty-five items were chosen and analyzed.PSEN1 mutations are the commonest cause of geneticearly-onset Alzheimer’s disease (EOAD), followed by PSEN2 andAPP mutations." (PMID 32973976, 2020). "Psen1 KO mice and knock-in (KI) mice with homozygous FAD-associated L435F mutations (Psen1LF/LF) are embryonic and perinatally lethal, precluding a more rigorous examination of the effect of Alzheimer's disease–causing Psen1 mutations on neurodegeneration." (PMID 32265300, 2020). "After failure to respond to standard medical treatment, she received an extensive workup, which ultimately revealed a PSEN1 mutation consistent with early-onset Alzheimer's disease." (PMID 33005464, 2020). "In the specific case of neuronal cells, some mutations in PSEN1/2 linked to Alzheimer’s disease leads to the partial inhibition of presenilins/γ-secretase activity, a result that end up in upregulated MAM function and ER-mitochondria communication." (PMID 32916960, 2020).